OGT (O-linked N-acetylglucosamine (GlcNAc) transferase)
Diseases named in the same sentence as OGT in open-access papers (continued):
Sharing a sentence is not in itself a finding about the gene and the disease.
cancer (continued). "Given the critical roles of OGT, such small molecule inhibitors may contribute substantially towards clarifying the function of OGT in cancer metastasis, and may be developed as clinically applicable anti-cancer therapeutic agents that can be used alone or in combination with other drugs." (PMID 33194731, 2020). "In this review, we summarize and discuss recent clues that OGT and O-GlcNAcylation intimately regulate the functions of the Polycomb group proteins at different levels especially during Drosophila melanogaster embryonic development and in human cancer cell lines." (PMID 30873122, 2019). "Additionally, we examined expression of O-GlcNAc, OGT and sCLU in normal and cancer tissues." (PMID 29435130, 2018). "Because these events, which influence either the HBP flux or OGT expression, are present in several types of tumors, protein hyper-O-GlcNAcylation is more and more considered to be an important driver for tumor onset, progression, malignancy and appearance of cancer hallmarks." (PMID 29865240, 2018). "OGT may be a target for cancer therapy in cancers where sCLU is upregulated." (PMID 29435130, 2018). "Therefore, manipulation of OGT or OGA activity might be a strategy for cancer treatment by manipulating metabolism." (PMID 28074064, 2017). "Together, our findings suggest that the OGT and c-Myc feedback loop is critical in tumor progression, and targeting these mediators may provide a mechanism-based therapeutic approach to regulate hyper-O-GlcNAcylation in human cancer." (PMID 27703839, 2016). "Together, our findings suggest that the OGT and c-Myc loop is critical in tumor progression, and targeting these mediators may represent a novel therapeutic strategy to regulate hyper-O-GlcNAcylation for the treatment of cancer." (PMID 27703839, 2016). "Indeed, keeping in mind that O-GlcNAcylation in normal cells should remain untouched, targeting OGT specifically in cancer cell in vivo may represent one of the most important challenges in this field." (PMID 23964270, 2013). "Abnormal O-GlcNAc levels and OGT and OGA expression have been observed in several cancer models, including cell lines and human tumor samples." (PMID 41513635, 2026). "OGT overexpression in HCT116 cells and other cancer cell lines reversed the decrease in XRCC4 levels under low-glucose conditions." (PMID 41513635, 2026). "Like FASN, OGT is overexpressed in cancers, including HCC, and is thought to participate in many hallmarks of cancer by regulating protein expression, activity, subcellular location, and interactions." (PMID 40684943, 2025). "Increased OGT expression and decreased in OGA expression have been reported in a number of human cancers." (PMID 38473405, 2024). "Inhibition of OGT in NCI-H460 cells and their xenograft model increases cancer cell sensitivity to proteasome inhibitors." (PMID 39285476, 2024). "This suggests that O-GlcNAc cycling is important in promoting cell proliferation pathways in several cancer types where OGA and OGT were both upregulated." (PMID 38601153, 2024). "O-GlcNAc modification, catalyzed by OGT (introducer) and OGA (remover), is a significant posttranslational modification with a noted increase in cancer contexts." (PMID 38609495, 2024). "However, the overall effect of OGT-mediated O-GlcNAcylation in cancer remains unknown." (PMID 38168435, 2024). "Recent evidence indicates that OGT and OGA are reciprocally controlled at the transcriptional level to maintain a balance of O-GlcNAc in healthy cells, but in cancer cells, the upregulation of both enzymes results in the promotion of tumor growth." (PMID 38473405, 2024). "In agreement with published studies in other cancers, we show that pharmacological downregulation of both GFPT1 and OGT inhibits cellular proliferation." (PMID 38732103, 2024). "And ubiquitination can regulate O-GlcNAcylation mainly shows the function of regulating OGT and OGA, thereby affecting cancer therapeutics resistance." (PMID 39487556, 2024).
cancer (continued). "Asthana and colleagues found in a mouse subcutaneous xenograft model of AML that inhibition of OGT function led to the differentiation and apoptosis of AML cells and the remission of cancer symptoms." (PMID 37596597, 2023). "FASN has been shown to be O-GlcNAcylated, which enhances the enzymatic activity of this fatty acid synthesizing enzyme, further supporting the intensive crosstalk between OGT, FASN, and the mTOR pathway in cancer." (PMID 37838167, 2023). "Finally, EIF3H could promote cancer progression in HCC via OGT." (PMID 37559097, 2023). "The invasive front of a tumor is the place where cancer cells are actively undergoing EMT, which further implicates the crucial role of OGT and O-GlcNAc in regulating EMT." (PMID 37838167, 2023). "In diet-induced obese mice, OGT expression and activity were increased relative to lean littermates and corresponded with higher levels of TET1-responsive cancer stem-like cell pathway member TARDBP." (PMID 37231419, 2023). "OGT deletion in macrophages reduces O‐GlcNAcylation and mature cathepsin B levels in the tumor microenvironment (TME), impeding cancer metastasis progression and chemotherapy resistance." (PMID 38116061, 2023). "Increased OGT expression enhances EZH2 stability via direct O-GlcNAcylation, thus promoting cancer cell migration and invasion." (PMID 37838167, 2023). "Together, these findings reveal the dynamic interaction between OGT/O-GlcNAc and the MEK/ERK signaling and their role in regulating cancer cell proliferation and tumor progression." (PMID 37838167, 2023). "In this review, we highlighted recent progress on the structural characterization of OGT and OGA, as well as their emerging roles in protein interaction networks in several cancer models." (PMID 36291918, 2022). "Compared to the parental cancer cells, FASN, SCD1 and FADS2 expression at the mRNA and protein level consistently downregulated in the GFPT1 and OGT knockdown cells." (PMID 35844792, 2022). "In line with this, O-GlcNAcylation levels and importance vary among different tissue types and OGT and OGA expression have different impacts and roles in different cancer types." (PMID 35868563, 2022). "OGT and OGA expression levels have been assessed in patients and normal samples of major human cancers." (PMID 36104770, 2022). "More interestingly, a significant correlation between the expression levels of OGT/OGA and the grade/stage of tumors or prognosis has been discovered, promoting mechanistic investigations of these enzymes in cancer." (PMID 36291918, 2022). "Herein, we highlight recent studies on the structural features of OGT and OGA, as well as the emerging roles and molecular mechanisms of their aberrant PPIs in rewiring cancer networks." (PMID 36291918, 2022). "O-GlcNAc cycling enzymes (OGT and OGA) regulate the functions of proteins in a broad range of cellular processes and their dysfunctions have been detected in many cancer types." (PMID 36291918, 2022). "We also discussed the potential of leveraging integrated approaches to dissect the molecular connections of OGT/OGA dysfunction and cancer phenotypes and manipulating their protein interactions as novel targets for anti-cancer therapeutic interventions." (PMID 36291918, 2022). "Slight-to-moderate correlations of OGT expression with TMB, MSI, and HRD were detected in numerous cancers." (PMID 35356257, 2022). "By integrating complementary approaches, the research in this area will aid in the identification of key protein contacts and functional modules derived from OGT/OGA that drive oncogenesis and will illuminate new directions for anti-cancer drug development." (PMID 36291918, 2022). "Research has demonstrated that OGT promotes EMT and invasion of cancer cells mainly via the junction with skeleton proteins." (PMID 36544170, 2022). "For O-GlcNAcylation, besides the regulation from metabolic flux, HBP enzymes, OGT and OGA are regulated by cancer-related pathways as well." (PMID 35201498, 2021).
cancer (continued). "In this review, we will first summarize how oncogenic signals regulate HBP enzymes, OGT and OGA in cancer." (PMID 35201498, 2021). "Accumulating experimental evidence has shown that cancer-related glucose metabolism dysregulations interact with increased glucose flux via HBP, leading to high OGT expression and global levels of OGlcNAcylation." (PMID 33828530, 2021). "Many cancer cells exhibit increased levels of glucose and glutamine uptake, leading to an abundant synthesis of UDP-GlcNAc that fuels OGT-mediated O-GlcNAcylation and the subsequent accumulation of NRF1 protein and the facilitation of the proteasome pathway." (PMID 33535386, 2021). "OGT and OGA-mediated O-GlcNAc cycling disturbances constitute a significant force for aberrant cell signaling in cancer." (PMID 33828530, 2021). "OGT inhibitors improve killing of cancer cells by PI3K inhibitors, suggesting OGT mediates resistance to PI3K inhibitors and possibly identifying a strategy to improve outcomes with kinase inhibitors in CLL patients." (PMID 34868034, 2021). "Atypical expression and activities of OGT and OGA have been reported in all human cancers studied thus far." (PMID 33916244, 2021). "In contrast, OGT expression level was significantly higher in grade II/III BC than grade I BC, suggesting that cellular O-GlcNAcylation correlated with cancer malignancy." (PMID 33535386, 2021). "Moreover, high OGT expression in primary cells is associated with an adverse clinical outcome in DLCL and MM as well as CLL, although a complete picture of the role of O-GlcNAcylation requires information on OGT and OGA protein expression along with a catalogue of the cancer specific O-GlcNAcome." (PMID 34868034, 2021). "Suggesting that by mediating the stabilization and activation of HIF-1α, OGT regulates HIF-1α target genes and functions in angiogenesis, as well as cancer metastasis." (PMID 33194731, 2020). "As expect, the results of western blotting assay shown that the OGT, DDX5, and O‐GlcNAcylation levels were significantly increased in all cancer cell lines compared to that in the NCM460 cell line." (PMID 30484950, 2019). "These recent works highlight once more the tight link that exists in cancer cells between PI3K/AKT/mTOR axis and OGT activity." (PMID 30356686, 2018). "Our discovery of the interaction between NRF1 and the OGT/HCF-1 complex has added a new regulatory axis to the proteasome bounce-back response and identified OGT as a new therapeutic target for sensitizing cancer cells to proteasome inhibitors." (PMID 29941490, 2018). "The flexible functional role of FH reflected here is attributed to the counteractive effect of OGT activity on AMPK signaling; this finding would valuably provide new molecular basis for developing effective cancer therapy in future." (PMID 31225435, 2017). "As shown by western blotting results, O-GlcNAcylated proteins levels, as well as OGA, OGT, and GFAT protein expression were much more elevated in cancer cell lines compared to the fetal cell line, in accordance with our previous study." (PMID 27252680, 2016). "In our study, both OGT and MGEA5 transcript levels were significantly related to cancer invasiveness." (PMID 25315705, 2015). "It should be emphasized that there are several constraints in interpreting results concerning the OGT and/or OGA activity in tumorigenesis and cancer progression." (PMID 25315705, 2015). "Enhanced O-GlcNAcylation level corresponding to increased OGT and decreased OGA expression is commonly observed in various cancers including bone, bladder, breast, bile duct, colon, leukemia, liver, lung, ovary, pancreas, and prostate." (PMID 25426101, 2014). "Future development should certainly include detailed analysis of the regulation of the promoters of OGT and OGA, and the study of the transcription factors that control the activities of these promoters in different types of normal and cancer cells." (PMID 23964270, 2013).
cancer (continued). "Increased protein O-GlcNAcylation and changes in OGT and/or OGA expression have now been described in different cancer types including breast (30–, 32), lung, colon, liver, bladder, endometrial prostate, and chronic lymphocytic leukemia (CCL) cells." (PMID 23964270, 2013). "As a whole, these results could open exploration of targeting OGT-FASN interaction, and may offer potential novel therapeutic solutions for cancer patients." (PMID 41550490, 2026). "This review systematically examines how O‐GlcNAcylation, OGT and OGA regulate distinct phases of autophagy in cancer, and how reprogramming autophagic flux through this post‐translational modification (PTM) influences metabolic plasticity and therapy resistance." (PMID 41540817, 2026). "Finally, translational studies should focus on developing and testing inhibitors of O-GlcNAcylation enzymes, such as OGT and OGA, in preclinical models of cancer and inflammatory diseases." (PMID 41350524, 2025). "In addition to TFRC, emerging evidence shows that, ROS-activated OGT suppresses ferroptosis through O-GlcNAcylation of FOXK2 and DJ-1 in certain cancers." (PMID 41350524, 2025). "For instance, OGA agonists could work synergistically with OGT or GFAT inhibitors to reduce O‐GlcNAcylation levels, potentially benefiting cancers and CVDs." (PMID 41394960, 2025). "Targeting OGT, OGA, and HBP pathways to modulate PCD may provide a novel approach to cancer treatment." (PMID 41059334, 2025). "In this cancer model, sGCα1 is suggested as a main component of the HBP, facilitating the activation of OGT enzyme, which catalyzes O-GlcNAcylation and activation of TRIB2, thereby contributing to the maintenance of a transformative phenotype of liver cancer cells." (PMID 39337539, 2024). "Additionally, pharmacological inhibition of OGT increases the expression of alanine aminotransferase 2 (GPT2), which can be targeted to reduce cancer cell survival and proliferation." (PMID 37838167, 2023). "Connections between OGT and ERK have also been uncovered in the context of cancer and cell division, with studies showing that inhibition of ERK signaling decreases O-GlcNAcylation and vice versa and that GlcNAcylation promotes ERK effects while OGT inhibition blocks them." (PMID 36951889, 2023). "Importantly, dual inhibition of OGT and FASN synergized to induce the death of cancer cells in vitro." (PMID 37838167, 2023). "Moreover, the role of APS in reducing OGT expression and increasing OGA expression allows APS to play an extensive role in cancer therapy." (PMID 36980207, 2023). "In addition, PKM2 regulation by OGT is augmented by epidermal growth factor (EGF), which is highly expressed in various cancers to promote cell survival and proliferation." (PMID 37838167, 2023). "Modulating the cycling of OGT and OGA via pharmacological means could thus show promise in preventing the growth and metastasis of cancer cells." (PMID 37107691, 2023). "Therefore, targeting O-GlcNAcylation through chemical inhibition of OGT and OGA enzymes has been proposed as an effective strategy for cancer treatment." (PMID 37689115, 2023). "Aberrant expression of OGT and OGA have been detected in many cancers." (PMID 35795059, 2022). "In our study, conspicuous effects of OGT expression in distinguishing cancers from noncancers were found in eight cancers (ACC, CHOL, LAML, OV, PAAD, SKCM, THCA, and UCS), indicating its potential in cancer prediction." (PMID 35356257, 2022). "In addition, high-OGT expression indicated longer DSS (LUAD and SKCM) and PFI (SKCM) in some cancers, while it suggested poor DSS (KICH, KIPAN, PCPG, and UCEC), PFI (COADREAD and PRAD), and DFI (COAD, COADREAD, KIRP, and PRAD) for multiple cancers." (PMID 35356257, 2022). "Taken together, our results suggest that ATM inhibition may promote SKOV3 cell apoptosis via suppressing hsa-miR-542-5p and elevating OGT and OGA expression, providing new insights into the application of ATM inhibitors in cancer immunotherapy." (PMID 35795059, 2022).
cancer (continued). "Although several compounds targeting cancer-specific metabolic abnormalities are currently assessed in clinical trials, the OGT inhibitors are still not yet, including in PC." (PMID 36439421, 2022). "Overall, it seems well defined that cellular O-GlcNAcylation is increased in response to anti-cancer therapies-induced stress but the molecular structure of some therapeutic agents could also interfere with UDP-GlcNAc metabolism and OGT activity." (PMID 36059648, 2022). "It is not known whether the regulation of PcG activity by sxc/OGT is important for cognitive function, but it can be noted that a series of PcG genes are associated with ID, and some of them are subject to regulation by OGT in the context of development or cancer." (PMID 35500025, 2022). "The first strategy is to target the enzymes OGT and OGA directly for cancer therapy." (PMID 36104770, 2022). "Perturbation of OGT/OGA PPI networks makes profound changes in the cell and may directly contribute to cancer malignancies." (PMID 36291918, 2022). "New studies in this direction are expected to provide a better understanding of OGT–protein interactions at the molecular level, further supporting that OGT acts as a multifaceted hub in the PPI networks of biology and disease, such as cancer." (PMID 36291918, 2022). "These analyses imply a strong connection between OGT/OGA PPIs and cancer." (PMID 36291918, 2022). "Taken together, we conclude that OGT inhibition in certain cancer cell lines leads to reduced cell proliferation without inducing cell death and this is at least partially dependent on p21." (PMID 35868563, 2022). "Similar to OGT, we used TCGA, TIMER2.0, and TISIDB to investigate the prognostic influence, pathological features, and clinical relevance of OGA expression in 33 major human cancer types." (PMID 36104770, 2022). "In 20 of the 32 cancers, the AUC values of OGT expression in differentiating cancer samples from noncancer samples were >0.7." (PMID 35356257, 2022). "In cancer cells, OGA transcript levels displayed compensatory variations upon alterations in O-GlcNAc status, whereas augmenting overall cellular O-GlcNAc levels leads to decreased transcript and translational efficiency of OGT." (PMID 35887161, 2022). "OGT expression enabled the conspicuous differentiation of SCLC samples and nonSCLC samples (sensitivity = 0.79, specificity = 0.86, and AUC = 0.88), similar to the results of the pan-cancer analysis." (PMID 35356257, 2022). "Thus, Hippo pathway components and O-GlcNAcylation regulatory enzymes (OGT and OGA) are potential targets for cancer diagnosis and treatment." (PMID 35740678, 2022). "Taken together, these results suggest OGT and O-GlcNAcylation may promote the growth of AML cells and constitute therapeutic targets in this cancer." (PMID 34868034, 2021). "Accumulating evidence suggests that OGT may act as a nutrient sensor that links HBP to oncogenic signaling and regulation of factors involved in glucose metabolism and cancer progression." (PMID 34204801, 2021). "Obviously, further investigations are required to elucidate if cancer and non-cancer cells utilize differential mechanisms to regulate OGT expression for maintaining cellular O-GlcNAc homeostasis." (PMID 33801653, 2021). "OGT and O-GlcNAcylation are regulated by cell type-specific mechanisms so that results in one cancer do not necessarily generalize to others." (PMID 34868034, 2021). "OGT was shown to O-GlcNAcylate pyruvate kinase M2 (PKM2), forcing formation of the dimer that shunts glucose into the pentose phosphate pathway to increase proliferation and growth of cancer cells." (PMID 34868034, 2021).